CD47 (CD47 molecule)
Diseases named in the same sentence as CD47 in open-access papers (continued):
Sharing a sentence is not in itself a finding about the gene and the disease.
cancer (continued). "Treatments aimed at blocking the interaction between CD47 and SIRPα are the most advanced in clinical trials and are currently being explored in the clinic for various human cancers." (PMID 38881902, 2024). "By inhibiting the CD47/SIRPα interaction, the “don’t eat me” signal is turned off, allowing macrophages and other myeloid cells to recognize and phagocytose cancer cells more effectively." (PMID 39040441, 2024). "miR-200a can affect nasopharyngeal carcinoma cell proliferation, migration, and invasion by regulating CD47, thereby providing a potential form of cancer therapy." (PMID 38383737, 2024). "This suggests that macrophages still display some anti-cancer activity, despite the inhibitory effects of CD47, and are important effector cells in final therapeutic outcome." (PMID 37066426, 2024). "The CD47 “Don’t Eat Me” blockade enhances the phagocytosis of cancer cells through macrophages, overcoming a key immune evasion mechanism used by tumors." (PMID 39275127, 2024). "Multifunctionalized iron oxide magnetic nanoparticles, which are carriers of anti-CD47 antibodies, not only help to retain their targeting activity but also achieve a short-term increase in delivery to cancer cells, accelerating cancer cell apoptosis." (PMID 38464520, 2024). "It has been discovered that a variety of cancer cells present high expression level of CD47 which correlates with poor prognosis of the disease." (PMID 38892394, 2024). "In this review, we highlight the difficulties in CD47/SIRPα targeted drug development for cancer immunotherapy, look into the future perspectives and explore potential solutions to improve CD47-SIRPα targeted drug development." (PMID 39040441, 2024). "CD47 is a transmembrane protein found on many cancer cells, contributing to the poor prognosis of cancers." (PMID 39457653, 2024). "CD47, a prominent “don’t eat me” signal expressed on various cancer cells, interacts with its receptor Sirpα on macrophages to inhibit phagocytosis." (PMID 39766137, 2024). "For most types of cancers, the CD47/Sirpα immune checkpoint has attracted the most attention in immunotherapy." (PMID 38832992, 2024). "This indicates the need to further evaluate the molecular basis for the many reported correlations between CD47 expression and cancer prognosis." (PMID 39201643, 2024). "CD47 is known to have a very important role in oncogenesis in many malignant diseases by stimulating the growth, invasion, and migration of cancer cells." (PMID 39201801, 2024). "Nonetheless, these results demonstrate induction of a generally potent anti-cancer antibody response to CIN-afflicted B16F10 in a CD47 KO context." (PMID 38805560, 2024). "Blocking immune checkpoint CD47/SIRPα is a useful strategy to engineer macrophages for cancer immunotherapy." (PMID 38383737, 2024). "Preclinical studies with anti-CD47 blocking antibodies have been promising in many cancer models, and humanized anti-CD47 monoclonal antibodies such as Hu5F9-G4 (Magrolimab) have been developed." (PMID 39194679, 2024). "Elevated expression of the CD47 protein in cancer cells provides a mechanism for immune evasion, particularly against phagocytosis." (PMID 39594611, 2024). "Given its role as an innate immune checkpoint, CD47 has emerged as a central target in the development of cancer immunotherapies." (PMID 39468077, 2024). "Briefly, CD47 is often overexpressed on the surface of cancer cells, acting as a “don’t eat me” signal." (PMID 39040441, 2024). "Various treatment strategies, including the use of antibodies targeting CD47, RNA interference for CD47 silencing, and agents modulating CD47 expression, have demonstrated efficacy in cancer treatment by disrupting the interaction between CD47 and SIRPα." (PMID 38543240, 2024). "CD47-SIRPα interaction is a biological process in which the protein CD47 on the surface of various cells, including cancer cells, interacts with SIRPα on the surface of macrophages." (PMID 38881902, 2024).
cancer (continued). "Cancer cells upregulate CD47 expression on their surface to avoid undergoing phagocytosis as a form of immune evasion." (PMID 38319147, 2024). "When comparing nearly all cancer types to normal tissue, we discovered that CD47 gene expression was higher in the former." (PMID 38720108, 2024). "We utilized a CD47-blocking antibody that disrupts the CD47-Sirpα interaction to induce cancer cell phagocytosis by the macrophages." (PMID 39766137, 2024). "There were strong connections via the GAS6-AXL/MERTK and THBS1-CD36/CD47/ITGA4/ITGB1/LRP1 axes between cancer cells (contributing ligands) and TAMs (contributing receptors)." (PMID 38169544, 2024). "Given that CD47 expression is dysregulated in a variety of cancers, improving our understanding of the cell-intrinsic signals regulated by this molecule will help advance the development of CD47-targeted therapies." (PMID 39039207, 2024). "Prominent among immune evasion pathways in GBM and other cancers, CD47 provides a “don’t eat me” signal by binding SIRPα expressed on macrophages and microglia." (PMID 39545414, 2024). "Of note, anti-CD47 therapies promote M1 polarization and phagocytosis of cancer cells by both M1 and M2 macrophages, with more prominent phagocytosis by M1 than M2, reversely to what we observed here with VISTA." (PMID 38553748, 2024). "Cancer cells can evade immune surveillance via the immune checkpoint CD47/SIRPα, and blocking this immune checkpoint is a useful strategy to engineer macrophages for cancer immunotherapy." (PMID 38383737, 2024). "Mn2+ can promote the phagocytosis of macrophages by increasing integrin expression and eliminating the immunosuppressive effect of CD47-overexpressing cancer cells." (PMID 38175694, 2024). "To date, 48 clinical trials on CD47 targeted therapy in various types of cancer have been registered in the USA (clinicaltrials.gov)." (PMID 38992659, 2024). "Recently, it was demonstrated that EVs not only significantly increased the phagocytosis of macrophages but also inhibited CD47 transcription and translation, exerting a strong anti-cancer effect." (PMID 39165926, 2024). "Blocking CD47 with specific antibodies can enhance the phagocytosis of cancer cells and is being investigated in combination with autophagy inhibitors to induce cancer cell death more effectively." (PMID 38892394, 2024). "Immunohistochemical staining results showed that a large amount of CD47 protein was distributed on NSCLC cancer cells, with a smaller amount present in the cytoplasm." (PMID 39652550, 2024). "In the TOV-112D and TOV-21G cell lines, CD47 overexpression promoted cancer cell growth and motility." (PMID 38832992, 2024). "The present paradigm, especially regarding cancer, is that only the CD47‐SIRPα signal counts and limited to innate immunity." (PMID 38362603, 2024). "In this review, we highlight the recent progress and difficulties in CD47/SIRPα targeted drug development for cancer immunotherapy, look into future perspectives, and explore potential solutions to improve CD47/SIRPα targeted drug development." (PMID 39040441, 2024). "Early phase clinical trials have shown promising results for CD47 blockade in various cancers, either as a single agent or in combination with other agents." (PMID 38638433, 2024). "Collagens, MIF, MDK, APP, and laminin were the most highly expressed, and the top ligand-receptor interactions were CAF derived THBS2/THBS3 with cancer cell CD47, and CAF-derived MDK with cancer cell NCL/SDC2/SDC4." (PMID 38525245, 2024). "As a result, strategies aimed at blocking the TSP-1/CD47 axis are currently becoming the focus of innovation in cancer therapy." (PMID 38832992, 2024). "In summary, our results suggest that HDAC6i enhances phagocytosis of cancer cells by macrophages, which is further increased upon CD47 blockade." (PMID 38414061, 2024).
cancer (continued). "The presence of CD47 in the majority of cancer types was observed to have a positive correlation with the infiltration of CD4 + T cell memory resting and CD4 + T cell Th2, in contrast to CD4 + T cell (non-regulatory) and CD4 + T cell Th1." (PMID 38720108, 2024). "The expression of specific biomarkers such as CD47, CD68, and CD163 is associated with these TAMs and has been studied extensively in relation to cancer prognosis." (PMID 39682556, 2024). "In coculture with macrophages, the anti-CD47 therapy significantly impaired the growth of the cancer cells as a single agent." (PMID 38483480, 2024). "CD47 is highly expressed on many cancers, and it binds to the inhibitory receptor SIRPa that is present on macrophages and other myeloid cells." (PMID 38483480, 2024). "The findings indicate that the association of CD47 and TNFRSF9 with CD8 + Tex in pan-cancer suggests their involvement in the dysregulation of CD8 + Tex in this type of cancer." (PMID 38720108, 2024). "The pseudotime trajectory analysis showed a similar SIRPα expression in the macrophages and an increase in CD47 expression in cancer cells from the OE-MLKL C57BL/6 orthotopic model." (PMID 39025845, 2024). "Powerful “don’t eat me” signals are sent to cancer cells when CD47 binds to SIRP, which is extensively upregulated on myeloid-linage hematopoietic cells including TAMs and MDSCs thus preventing phagocytosis." (PMID 38165484, 2024). "In other preclinical studies, the combination of CD47 mAb and cabazitaxel exhibited a significant anti-cancer effect in TNBC." (PMID 39040441, 2024). "To determine the impact of MSC CD47 or PD-L1 expression on macrophage phagocytosis, we repeated the cancer cell phagocytosis assay with the addition of SIRP-α and PD-1 receptor-blocking antibodies." (PMID 39310770, 2024). "The CD47–signal-regulatory protein α axis prohibits the uptake of cancer cells by APCs, which eventually leads to failure in the establishment of anti-cancer adaptive immunity." (PMID 38474078, 2024). "As such, the CD47–SIRPα protein complex has been recognized as a potential therapeutic target in cancer and inflammation." (PMID 37999357, 2023). "It will explore its interactions with other TME components, its impact on various immunotherapy outcomes, and the potential implications of CD47-targeted therapies in cancer treatment." (PMID 38188674, 2023). "Overall, the diverse signaling pathways activated by CD47 underscore its importance in regulating cellular responses and its potential as a therapeutic target for cancer treatment." (PMID 38188674, 2023). "In numerous cancers, TIGIT signaling negatively regulates antitumor immunity, and CD47 overexpression has been reported to be associated with poor survival and a higher rate of progression to AML in MDS patients." (PMID 36816361, 2023). "The use of an anti-CD47 antibody not only enhances phagocytosis of cancer cells by macrophages but also facilitates antigen presentation by macrophages to ultimately activate cytotoxic T cells." (PMID 37143666, 2023). "Previous studies have shown that CD47 can act as a predictor of various cancers, affecting cell proliferation, migration, and apoptosis in various malignancies through the PI3K/Akt pathway." (PMID 37783914, 2023). "It is also important to note that CD47 is overexpressed in many types of cancer, including ovarian, brain, and lung, as well as in cancer stem cells." (PMID 37408232, 2023). "THBS1 can bind to CD47 in hematological tumors, thereby inhibiting the immune response to cancer cells." (PMID 37771777, 2023). "As for CD47, multiple transcriptional mechanisms have been reported to promote CD47 expression in cancer." (PMID 36823443, 2023). "An elaborate discussion of CD47 regulation and its function in cancer immunotherapy will be presented in the following sections." (PMID 36882399, 2023). "We confirmed the expression of CD47 in a wide range of cancer cells, consistent with previous reports." (PMID 37444515, 2023).
cancer (continued). "CD47 enables cancer cells to avoid being phagocytosed and destroyed by macrophages, thereby facilitating their evasion of the immune system." (PMID 37508523, 2023). "The CD47/SIRPα axis is well known to mediate immune escape by promoting cancer resistance to phagocytosis." (PMID 37848444, 2023). "In this study, we show that the activation of GPR84 by the synthetic agonist 6-OAU can synergize with the blockade of CD47 on cancer cells to induce phagocytosis of cancer cells by macrophages." (PMID 37709767, 2023). "By blocking CD47, researchers aim to enable the immune system to recognize and attack cancer cells more effectively." (PMID 38125492, 2023). "For instance, CD47 is expressed on many cancer cells, and binding of CD47 to signal-regulatory protein α (SIRPα) on macrophages results in inhibition of macrophage phagocytic activity." (PMID 37723178, 2023). "Blockade of the CD47-SIRPα interaction primarily leads to phagocytosis of cancer cells, but a significant AE is severe hemolysis due to RBCs expressing CD47." (PMID 37920162, 2023). "Low CD47-expressing cancer cells are more prone to phagocytosis; however, the phagocytic clearance is sometimes thwarted due to reverse signaling activities that support anti-apoptotic effects on these cells." (PMID 37848444, 2023). "In recent years, CD47 blockade has emerged as a potential therapeutic strategy in cancer immunotherapy." (PMID 38188674, 2023). "CD47 has high levels of expression in malignant cancer cells, which binds to SIRP-α to release the “don't eat me” signal and prevents mononuclear macrophages from phagocytosing the cells." (PMID 37719086, 2023). "Immunohistochemic3al staining showed the expression of STC1, AKR1B1, and CD47 was increased along cancer invasion in CRC samples." (PMID 36816947, 2023). "Multiple strategies have been devised to either block CD47 or SIRPα, and have proven effective in anti-cancer therapy." (PMID 38035101, 2023). "When CD47 on the cancer cell surface engages with SIRPα on MΦ, it sends a “Don’t-eat-me” signal to prevent phagocytosis of cancer cells by MΦ." (PMID 38239396, 2023). "The expression of CD47 on cancer cells acts as a “don’t eat me” signal to prevent cancer cells from being phagocytosed because CD47 binds signal regulatory protein α (SIRPα) on APCs, including DCs and macrophages." (PMID 37208386, 2023). "Based on past research, a high level of activation of SIRPα-CD47 signaling allows cancer cells to avoid immune detection and elimination by professional phagocytes." (PMID 37291116, 2023). "CD47 on cancer cells interacts with the inhibitory receptor signal regulatory protein alpha (SIRPα), which is expressed in phagocytes." (PMID 37894750, 2023). "CD47 is also expressed on cancer cells and plays a role in preventing phagocytosis by binding to SIRPα expressed in macrophages." (PMID 37545625, 2023). "High levels of CD47 expression on cancer cells have consistently correlated with poor clinical response rates and worse overall survival (OS) in patients receiving immunotherapy." (PMID 38188674, 2023). "When comparing the cancer cell lines, we found that the overall efficiency of forming THCs was more pronounced in low CD47-expressing C4-2 cells relative to high CD47-expressing 22Rv1 or DU145 cells co-cultured with macrophages." (PMID 37848444, 2023). "The success and advancements in CD47 cancer immunotherapy have sparked optimism and paved the way for innovative approaches in treating a wide range of noncancerous conditions." (PMID 38125492, 2023). "Results from in vitro and in vivo studies have consistently shown that CAR T-cells that CD47 targeted CAR T-cells can efficiently eliminate cancer cells while sparing normal cells." (PMID 38188674, 2023). "Recent progress has been made in targeting CD47 for cancer immunotherapy, and several CD47/SIRPα axis inhibitors have been developed for clinical trials with a favorable antitumor response in solid tumors and hematological malignancies." (PMID 36575242, 2023).
cancer (continued). "Tumor cells overexpress CD47 in many cancers and by this, they avoid their removal by TAMs and other phagocytes." (PMID 37359522, 2023). "SIRPγhi cancer cells display stemness-related properties and contribute to immune escape signals by sustaining CD47 expression, which halts macrophage-mediated phagocytosis in SIRPγhi and SIRPγlo/− tumor cells." (PMID 38164743, 2023). "The CD47/SIRPα interaction is another therapeutic target for human solid tumors: CD47 is a unique cell-surface marker expressed by human cancers; SIRPα is a protein expressed on macrophages and dendritic cells." (PMID 36827121, 2023). "The immune evasion of cancer cells is closely related to the proteins present on the cell surface, such as CD47, which is ubiquitously expressed on the membrane of solid tumor cells and sends a “do not eat me” signal to phagocytic cells." (PMID 36895440, 2023). "In fact, anti-CD47 therapy was shown to target and eliminate cancer stem cells in several solid tumor models." (PMID 37468567, 2023). "A wide variety of cancer cells have been found to exploit this mechanism to escape innate immune surveillance through overexpression of CD47." (PMID 36650558, 2023). "Immune surveillance escape occurred by hijacking the corresponding inhibitory pathways via overexpressed checkpoint genes such as PD-L1 and CD47; thus, phagocytosis checkpoints have emerged as essential checkpoints for cancer immunotherapy." (PMID 38022584, 2023). "For CD47 blockade to benefit cancer patients, strategies to widen its therapeutic window are required." (PMID 37958404, 2023). "Our simulation results extend the present understanding of cooperative effects in CD47–SIRPα interactions and thus can influence advancements of new cancer treatments." (PMID 37999357, 2023). "CD47-targeted therapies have shown potential in cancer immunotherapy, but they also present challenges that need to be addressed." (PMID 38188674, 2023). "The binding of CD47 and SIRPα leads to the inhibition of phagocytic activity in macrophages, which is beneficial for normal cells but also allows cancer cells to evade immune detection and elimination." (PMID 37375166, 2023). "CD47-targeted therapy offers a promising approach to improving cancer treatment outcomes by blocking CD47 and helping immune cells find and destroy cancer cells." (PMID 38188674, 2023). "LILRB1 has gained increasing attention as it has been demonstrated to function as a phagocytosis checkpoint on macrophages by recognizing HLA class I, which represents a ‘Don’t Eat Me!’ signal that impairs phagocytic uptake of cancer cells, similar to CD47." (PMID 37781391, 2023). "In certain cancer cell lines, combining CD47 blockade with desialylation improved IgA-mediated ADCC, effectively overcoming resistance that remained when blocking only one checkpoint interaction." (PMID 37444515, 2023). "It is conceivable that the fusion WT NVs platform can be extended to concurrently targeting to other checkpoints for synergetic cancer immunotherapy except PD‐1/PD‐L1 and SIRPα/CD47, such as CTLA‐4, LAG‐3, TIGIT and so on." (PMID 37974395, 2023). "Overall, these clinical trials are testing the safety and efficacy of CD47-targeted therapies in various cancer types and stages." (PMID 38188674, 2023). "We also noted that anti-CD47 when combined with olaparib downregulated immunosuppressive myeloid markers in cancer cells specifically, TGFBR1 and CSF1R, which has been shown to correlate with therapy resistance." (PMID 37468567, 2023). "In cancer cells, blockade of CD47 actively modulates the immune response and efferocytosis to initiate antitumor cytotoxicity." (PMID 37368493, 2023). "Accordingly, SEs of CD47 discovered in cancer cells were accompanied by newly generated super-enhancers, increasing the likelihood of high CD47 expression." (PMID 37190100, 2023).